RPS9 (ribosomal protein S9)
Diseases named in the same sentence as RPS9 in open-access papers:
RPS9 is named in the same sentence as 40 diseases in open-access papers, as found by Europe PMC text mining. Sharing a sentence is not in itself a finding about the gene and the disease. The quoted sentences say what the papers report.
osteosarcoma (6 papers, 2010 to 2023). A usually aggressive malignant bone-forming mesenchymal neoplasm, predominantly affecting adolescents and young adults. "In response to stress, uS3/RPS3, uS4/RPS9, uS17/RPS11, eS24/RPS24, eL6/RPL6, uL13/RPL13A, eL14/RPL14, eL30/RPL30, eL42L/RPL36AL, and RACK1 in U2OS (human osteosarcoma) cells have O-linked β-N-acetylglucosamine (O-GlcNAc) modifications." (PMID 37047306, 2023). "Decreased levels of RPS9 were associated with accumulation of cells in G1/(G0) and p21 induction in U2OS osteosarcoma cells." (PMID 20221446, 2010). "Suppressing RPS9 blunts osteosarcoma cell growth via inactivating MAPK signaling." (PMID 35836470, 2022). "RPS9 promoted osteosarcoma tumor growth by activating MAPK signaling pathway." (PMID 33305312, 2021). "The localization of endogenous and ectopic RPS9 was analyzed in the U2OS osteosarcoma cell line." (PMID 23285058, 2012). "What's more, RPS9 can also exerts tumor stimulative functions in Osteosarcoma through Inactivation of MAPK Signaling Pathway24, which gives us more evidence that RPS9 may play a promoting role in tumorigenesis." (PMID 35281852, 2022).
breast carcinoma (5 papers, 2021 to 2025). "However, low ribosomal protein S9 (RPS9) expression, which was identified as a downregulated “node,” is associated with poor survival in breast cancer patients." (PMID 40714319, 2025). "While the role of RPS9 in breast cancer is unknown, decreased RPS9 expression has been observed in other solid tumors including pancreatic cancer." (PMID 33718123, 2021). "Contradicting our results, previous studies have shown that low expression levels of ribosomal proteins RPS9, RPS14, RPS27, RPL11 and RPL14 are related to a poor overall survival in breast cancer patients, especially in TNBC." (PMID 37888706, 2023). "In a previous report, Fang and Zhang used integrated bioinformatics analyses and identified that low mRNA expression of RPL11, RPS14, RPS9, and RPL10A were related to a worse overall survival of breast cancer patients." (PMID 33718123, 2021).
colon cancer (5 papers, 2013 to 2024). "For instance, the knockdown of RPS9 in HT29 colon cancer cells induces growth inhibition and cell cycle arrest at the G2/M phase by downregulating the cell cycle regulator CDK1." (PMID 38542474, 2024). "Knockdown of ribosomal protein S9 (RPS9) inhibits the growth of human colon cancer cells at the G2/M phase by downregulating CDK1 expression at the promoter level." (PMID 37311884, 2023). "Similar to treatment with apigenin, knockdown of RPS9 inhibited the growth of human colon cancer cells at the G2/M phase by downregulating cyclin-dependent kinase 1 (CDK1) expression at the promoter level." (PMID 24009741, 2013). "Other than that, knockdown of RPS9 induced G2/M arrest of colon cancer cells by downregulating CDK1 expression at the promoter level and dysregulation of RPS9 may be involved in microsatellite instability of colorectal cancer 31] [32." (PMID 35281852, 2022).
glioma (4 papers, 2010 to 2022). A benign or malignant brain and spinal cord tumor that arises from glial cells (astrocytes, oligodendrocytes, ependymal cells). "In contrast to U343MGa Cl2:6 cells and other glioma cell lines tested, that did not undergo apoptosis, a significant number of HeLa cervical carcinoma cells showed signs of membrane blebbing, and then detached from the dish 36–48 hours after RPS9 silencing." (PMID 20221446, 2010). "We found that endogenous RPS9 could be efficiently silenced in U343MG and in U87MG glioma cells whereas no change in RPS9 expression was seen in U1242MG cells upon siRPS9 transfection." (PMID 20221446, 2010).
anemia (2 papers, 2019 to 2022). A reduction in the number of red blood cells, the amount of hemoglobin, and/or the volume of packed red blood cells. "Detailed analyses showed that mutation in rps9 could lead to anemia, accompanied by severe morphological abnormalities." (PMID 31619461, 2019). "Blood count analysis was performed in female Rps9 D95N mutants and revealed mild anemia together with significantly decreased white blood cell counts, lymphopenia, and relative monocytosis in comparison with WT female littermates at 18 months of age." (PMID 35235349, 2022). "Analysis of this mutant demonstrates that rps9 disruption leads to impairment of erythrocyte maturation, resulting in anemia." (PMID 31619461, 2019). "Treatment of previously used agents including L-leucine and dexamethasone was able to alleviate the anemia phenotype in rps9 mutant." (PMID 31619461, 2019). "Although no rps9 mutation has been reported in any cases of anemia, this study suggests that rps9 can be a potential candidate for DBA or other human anemia diseases." (PMID 31619461, 2019). "Overall, our study suggests that rps9 can be a candidate for human anemia disease." (PMID 31619461, 2019).
colorectal cancer (2 papers, 2017 to 2022). A primary or metastatic malignant neoplasm that affects the colon or rectum. "Previously, RPS9 has been reported to have an oncogenic role in colorectal cancer, neuroblastoma cells and NSCLC 28-30." (PMID 35281852, 2022).
lung carcinoma (2 papers, 2022). "The role of RPS9 on the occurrence and metastasis of lung cancer needs more research." (PMID 35281852, 2022). "It was observed that BRCAT54 was downregulated in lung cancer and it regulates the expression of genes involved in the JAK-STAT and calcium pathways by binding to RPS9, thereby suppressing tumorigenesis." (PMID 35200096, 2022).
pancreatic cancer (2 papers, 2021 to 2022). "Previous studies have suggested that RPS9 dysregulation was involved in tumorigenesis, such as pancreatic cancer, head, and neck cancer (such as head and neck squamous cell carcinoma) and so on 13-15." (PMID 35281852, 2022).
cataract (1 paper, 2022). Partial or complete opacity of the crystalline lens of one or both eyes that decreases visual acuity and eventually results in blindness. "Young Rps9 D95N mice were indistinguishable from WT littermates, but long-term follow-up revealed a notable premature aging phenotype beginning at about 9 months of age, consisting of hair loss, graying, kyphosis, chest deformation, hunchback postures, eye cataracts, and poor body condition." (PMID 35235349, 2022).
Cerebral ischemia (1 paper, 2021). Restriction of arterial blood supply to the brain associated with insufficient oxygenation to support the metabolic requirements of the tissue. "Moreover, the hub genes RPS9 and RPL8 of PPI network analysis were significantly increased in the brain tissue after cerebral ischemia and hemorrhage." (PMID 33613646, 2021).
Diamond-Blackfan anemia (1 paper, 2012). A congenital aregenerative and often macrocytic anemia with erythroblastopenia. "While RPS9 has so far not been associated with Diamond Blackfan anemia, studies on RPS9 and artificial RPS9 mutants may provide clues to the functions and behaviors of other RPs." (PMID 23285058, 2012).
hyperandrogenism (1 paper, 2024). Excessive secretion of androgens from the adrenal glands or gonads. "RPS9 is a ribosomal gene and SMAD modulates ovarian steroidogenesis; its defect may lead to hyperandrogenism, becoming a potential drug target for PCOS treatment." (PMID 39457593, 2024).
Infertility (1 paper, 2022). "Furthermore, the Wilcox test revealed a significant association of RPS9, DUT, CDKN2C and MARF1 genes with infertility in the red, blue, and turquoise modules." (PMID 35603216, 2022).
insulinoma (1 paper, 2015). "The increased monosomes detected in islets and the IRE1α-deleted insulinoma line were accompanied by basally increased RPS9 and RPSA protein, but not increased mRNA levels." (PMID 26469762, 2015). "Western blotting for the ribosomal small subunit proteins RPS9 and RPSA in cytosolic and membranous fractions from glucose-stimulated floxed Ire1αFe/Fe insulinoma cells indicated Ire1α deletion in vitro disrupted glucose-stimulated recruitment of the ribosome to the membranous fraction." (PMID 26469762, 2015).
myeloma (1 paper, 2021). "Studies had shown that RPS9 expression was associated with OS and extramedullary infiltration in myeloma." (PMID 33305312, 2021).
non-small cell lung carcinoma (1 paper, 2025). A group of at least three distinct histological types of lung cancer, including non-small cell squamous cell carcinoma, adenocarcinoma, and large cell carcinoma. "The long non-coding RNA divergent transcript of MRPS30 can interact with RPS9, inhibit JAK-STAT signaling, and inhibit the progression of non-small cell lung cancer." (PMID 39913623, 2025).
obstructive uropathy (1 paper, 2022). "In addition, at age 18 months, 8 of 10 male Rps9 D95N mutants but 0 of 15 male controls (χ2 test, P < 0.0001) suffered from obstructive uropathy." (PMID 35235349, 2022).
renal fibrosis (1 paper, 2025). A final common manifestation of a wide variety of chronic kidney diseases characterized by glomerulosclerosis and tubulointerstitial fibrosis. "Further analysis yielded three ribosome biogenesis-related DEGs, including Rps19, Rps9, and Isg20, which were significantly upregulated in renal fibrosis samples." (PMID 40622935, 2025). "The expression levels of Rps19, Isg20, and Rps9 were significantly upregulated in renal fibrosis samples from both the GSE42303 and GSE121190 datasets." (PMID 40622935, 2025). "Among these, Rps19, Rps9, and Isg20 were significantly upregulated in UUO-induced renal fibrosis mouse kidney samples, with Isg20 showing the highest level of upregulation." (PMID 40622935, 2025).
schwannoma (1 paper, 2014). A benign, usually encapsulated slow growing tumor composed of Schwann cells. "We then tested the potency of the three drugs to down-regulate Pmp22 expression in rat RT4 schwannoma when normalised to the levels of both Actb and Rps9 housekeeping genes." (PMID 25491744, 2014).
Shwachman-Diamond syndrome (1 paper, 2018). "Gene expression profiles of bone marrow mononuclear cells from patients with Shwachman-Diamond syndrome revealed significant downregulation of RP genes, including RPS9, RPS20, RPL6, RPL15, RPL23, and RPL29, or upregulation of RPS27." (PMID 29954325, 2018).
Takayasu disease (1 paper, 2019). "More experiments are needed to address the link between rps9 and Takayasu disease or ribosomal deficiency and vascular integrity in general." (PMID 31619461, 2019). "A recent genome-wide association study has implicated rps9 as a candidate for Takayasu disease, which is a rare inflammatory disease that typically damages the aorta and its major branches." (PMID 31619461, 2019).
tumor (13 papers, 2002 to 2025). "Three of the identified proteins, RPL7a, RPL14, and RPS9, are ribosomal proteins involved in protein synthesis, control of cellular transformation, tumor growth, aggressiveness, and metastasis." (PMID 40229247, 2025). "Previously, RpS9 knockdown was shown to significantly reduce the rate of protein synthesis and cell proliferation in primary human fibroblasts and tumor cell lines." (PMID 21151574, 2010). "From another angle, it is possible that inhibiting the expression or function of some ribosomal proteins, such as RPS9, would be one way to reinitiate differentiation processes and stop the growth of rapidly proliferating malignant tumor cells." (PMID 20221446, 2010). "In contrast to our findings, a previous study showed that the inhibition of RPS9 expression may be one efficient way to inhibit rapidly proliferating tumor cells." (PMID 23723971, 2013). "Inhibiting the expression of certain ribosomal proteins, such as RPS9, could be one efficient way to reinitiate differentiation processes or to induce senescence or apoptosis in rapidly proliferating tumor cells." (PMID 20221446, 2010). "NPM1 is an abundant protein in tumor cell lines and hence NPM1 is more likely to regulate RPS9 localization than the other way around." (PMID 23285058, 2012). "All four cell lines as well as 10 primary human tumour samples plus adjacent normal kidney tissues were tested for CXCR4 and CXCL12α as well as for RPS9-mRNA expression." (PMID 11953881, 2002). "In this context, RPS9 is involved in tumorigenesis in both positive and negative ways depending on different tumor type and regulatory mechanism." (PMID 35281852, 2022). "Additionally, quantitative real-time PCR (qRT-PCR) results showed the expressions of RPS9, RPS14, RPS27, RPL11 and RPL14 were notably down-regulated in tumor tissues of 16 TNBC patients when compared with those in 21 cases of non-TNBC patients." (PMID 33305312, 2021). "Transcriptional profiles identified 39 genes that differentiated between 19 'metastatic' and 35 'non-metastatic' tumours, with molecular pathways involved in protein translation most strongly represented (MRPL33, RPL12, RPL27A, RPS5, RPS9)." (PMID 21385341, 2011).
cancer (8 papers, 2010 to 2024). A tumor composed of atypical neoplastic, often pleomorphic cells that invade other tissues. "Using a set of cancer cell lines we investigated the proliferation and phenotypic response to RPS9 depletion." (PMID 20221446, 2010). "Importantly, two genes associated with improved long term survival, HPSE and RPS9, were identified to be hypomethylated in mammary glands of rats exposed prepuberally to GEN or to GEN + BPA respectively, reinforcing the suggested cancer suppressive properties of GEN." (PMID 28505145, 2017). "The most enriched KEGG pathways were related to the ribosome (RPS5, RPS9), focal adhesion signaling pathways (FGL, SPP1), synaptic vesicle cycle (CLTC), and ether lipid metabolism (ENPP2), which were related to the invasion and metastasis of cancer." (PMID 36276156, 2022).
infection (4 papers, 2015 to 2022). The state of being infected such as from the introduction of a foreign agent such as serum, vaccine, antigenic substance or organism. "The compound was concentrated in the perinuclear region, and the RPS9 was a potential target during early infection." (PMID 34834059, 2021). "We could identify reference genes that are suitable for expression profiling during the infection process in planta and combined with the germ tube stage: CytB/PDK or CytB/GAPDH and Elf3/RPS9 or PKD/GAPDH are suitable reference gene combinations." (PMID 26404265, 2015).
adenocarcinoma (1 paper, 2022). A common cancer characterized by the presence of malignant glandular cells. "To examine the potential role of RPS9 in NSCLC tissue, we firstly analyzed RPS9 mRNA levels in NSCLC data from TCGA database via UALCAN, the results confirmed that RPS9 was highly expressed in primary adenocarcinoma samples compared with normal samples." (PMID 35281852, 2022).
neurological diseases (1 paper, 2013). "Seven (12.7%) of the DEGs were associated with neurological diseases (BAT3, HS6ST1, IFI44L, RFC3, RPS9, STRC and TCF19) according to the IPA analysis (p = 0.003)." (PMID 23593218, 2013). "Remarkably, about 13% of the DEGs in FGF2 treated S252W fibroblasts were associated with neurological diseases (BAT3, HS6ST1, IFI44L, RFC3, RPS9, STRC and TCF19)." (PMID 23593218, 2013).
RPS9 also shares sentences with these, for which no sentence is quoted: cervical carcinoma (2 papers); nasopharyngeal carcinoma (2); COVID-19 (1); Diabetes (1); embryonal carcinoma (1); encephalitis (1); HCMV infection (1); hemorrhage (1); liver cancer (1); lymphoma (1); lymphopenia (1); metastatic disease (1); neuroblastoma (1); pulmonary disease (1).